FIP1L1 (factor interacting with PAPOLA and CPSF1)
Diseases named in the same sentence as FIP1L1 in open-access papers (continued):
Sharing a sentence is not in itself a finding about the gene and the disease.
hypereosinophilic syndrome (26 papers, 2009 to 2026). Hypereosinophilic syndrome (HES) constitutes a rare and heterogeneous group of disorders, defined as persistent and marked blood eosinophilia and/or tissue eosinophilia associated with a wide range of clinical manifestations reflecting eosinophil-induced tissue/organ damage. "The presence of the Fip1-Like1-platelet-derived growth factor receptor alpha (FIP1L1-PDGFRα) fusion gene is a rare cause of hypereosinophilic syndrome requiring a distinct therapeutic approach." (PMID 42130655, 2026). "It is known that hypereosinophilic syndrome is associated with structural variants, including chromosome translocations, leading to gene fusions, with FIP1L1 and PDGFRA being the genes most frequently implicated." (PMID 41190063, 2025). "The patient was treated for FIP1L1-PDGFRA clonal hypereosinophilic syndrome with associated eosinophilic myocarditis and intracardiac thrombus." (PMID 37692703, 2023). "Mutations in FIP1L1-PDGFRα (FIP1-Like-1 (FIP1L1)-platelet-derived growth factor receptor α (PDGFRα) confers resistance to imatinib in hypereosinophilic syndrome." (PMID 36700235, 2022). "Cardiac involvement is a significant and unpredictable complication of hypereosinophilic syndrome, particularly prevalent in patients carrying the FIP1L1-PDGFRA fusion." (PMID 40384954, 2025). "It confirmed a diagnosis of hypereosinophilic syndrome with the FIP1L1‐PDGFRA fusion gene, indicating myeloid neoplasm with eosinophilia and PDGFR-A rearrangement." (PMID 38887335, 2024). "We herein report a case of a young male patient with hypereosinophilic syndrome and FIP1L1-PDGFRA rearrangement who presented with asthma, transient ischemic attacks (TIA), and confusion." (PMID 31737382, 2019). "FIP1L1 which encodes FIP 1-like, primarily characterised as a fusion protein (FIP1L1-PDGFRA) in hypereosinophilic disorders." (PMID 27535281, 2016). "FIP1L1-PDGFRA was first discovered as a recurrent rearrangement in Hypereosinophilic Syndrome in 2003, and response to imatinib was demonstrated." (PMID 26457233, 2015). "The FIP1-like-1-platelet-derived growth factor receptor alpha (FIP1L1-PDGFRα) fusion oncogene is the driver factor in a subset of patients with hypereosinophilic syndrome (HES)/chronic eosinophilic leukemia (CEL)." (PMID 25431951, 2014). "In contrast to other antieosinophilic biologics, mepolizumab is approved for use in other conditions, namely chronic rhinosinusitis with nasal polyps (CRSwNP), eosinophilic granulomatosis with polyangiitis (EGPA), and FIP1L1-PDGFRA-negative hypereosinophilic syndrome (HES)." (PMID 36982789, 2023). "Underlying eosinophil-related diseases included FIP1L1-PDGFRA-associated chronic myeloid neoplasm (n = 4), Eosinophilic Granulomatosis with Polyangiitis (n = 9), lymphocytic (n = 1) and idiopathic (n = 29) variants of hypereosinophilic syndrome." (PMID 33737704, 2021). "Imatinib is thus approved for multiple indications such as Kit-mutant gastrointestinal stromal tumors (GIST), systemic mastocytosis, Ph+ acute lymphoblastic leukemia, myeloproliferative neoplasms with PDGFR gene-rearrangement, and hypereosinophilic syndrome with FIP1L1-PDGFRa." (PMID 34829820, 2021). "In addition, we found that imatinib, which is effective in FIP1L1-PDGFRalpha rearrangement positive hypereosinophilic syndromes, was highly effective also in cases bearing this KITM541L variant." (PMID 25015329, 2014). "Interestingly, masitinib is also very active against the protein FIP1L1-PDGFRα, which is generated from an internal deletion of chromosome 4 and is responsible for the induction of hypereosinophilic syndrome." (PMID 19789626, 2009). "Triptolide suppressed FIP1L1-PDGFRα expression, as well as downstream activation of STAT3, Erk and Akt to induce apoptosis of imatinib-resistant hypereosinophilic syndrome cells." (PMID 36700235, 2022).
hypereosinophilic syndrome (continued). "Thus, it is not unreasonable to speculate that the usage of molecular techniques for the early diagnosis of suspected FIP1L1-PDGFRA-positive leukemias, can modify the diagnostic criteria of hypereosinophilic syndrome with significant impact in undesirable morbidity and mortality." (PMID 19187542, 2009). "Mepolizumab, administered intravenously at 750 mg every 4 weeks, has been demonstrated to be safe and effective as a corticosteroid-sparing agent in patients suffering from FIP1L1-PDGFRA negative hypereosinophilic syndrome (HES)." (PMID 29896203, 2018). "A bone marrow biopsy showed “chronic pattern compatible with hypereosinophilic syndrome” while genetic tests to search for mutations including Bcr/Abl, JAK2 V617F, c-KIT D816V, and FIP1L1-PDGFRA were negative." (PMID 29896203, 2018). "The FIP1L1-PDGFRA fusion gene, which leads to the constitutive activation of PDGF receptor, is the most frequent genetic defect in hypereosinophilic syndrome (HES), and has been found in approximately 50% of chronic eosinophilic leukaemia (CEL) patients." (PMID 29940987, 2018). "A constitutively activated FIP1L1-PDGFRA fusion TK has been identified in patients with CEL with or without an accompanying hypereosinophilic syndrome (HES)." (PMID 26543328, 2015).
myeloproliferative neoplasm (10 papers, 2009 to 2025). A clonal hematopoietic stem cell disorder, characterized by proliferation in the bone marrow of one or more of the myeloid (i.e., granulocytic, erythroid, megakaryocytic, and mast cell) lineages. "A 9-month-old boy with a FIP1L1::RARA fusion-associated myelodysplastic/myeloproliferative neoplasm-like overlap syndrome was also reported." (PMID 36776354, 2022). "Molecular cytogenetic analysis (FISH) for PDGFRA, PDGFRB, and FIP1L1 rearrangements returned negative, effectively ruling out an underlying myeloproliferative neoplasm." (PMID 40943043, 2025). "FIP1L1::PDGFRA fusion, one of the major oncogenic fusion genes of myeloproliferative disorders, is another example of JM dysfunction." (PMID 38071343, 2023).
myeloid neoplasm (9 papers, 2012 to 2026). Proliferation of myeloid cells originating from a primitive stem cell. "FIP1L1::RARA is a rare alternative fusion type associated with myeloid neoplasm composed of 426 amino acids (AA) from the N terminus of FIP1L1 and 403 AA from the C terminus of RARA." (PMID 36776354, 2022). "Characteristics of reported myeloid neoplasms with FIP1L1::RARA." (PMID 36776354, 2022). "Several patients with FIP1L1::RARA were diagnosed as other myeloid neoplasms." (PMID 36776354, 2022). "Unfortunately, we were not able to test this hypothesis in the current study, as we could not examine EO derived from patients with FIP1L1::PDGFRA-mutated myeloid neoplasms." (PMID 38247864, 2024). "Bone marrow examination showed increased hypercellularity, and molecular testing was positive for FIP1L1-PDGFRA fusion, confirming a myeloid neoplasm with hypereosinophilia." (PMID 42130655, 2026). "Obvious transcriptomic differences between APL with FIP1L1::RARA and myeloid neoplasms were identified." (PMID 36776354, 2022). "Secondly, the number of APL patients with FIP1L1::RARA and other myeloid neoplasms is extremely limited, and the credibility of the results is limited." (PMID 36776354, 2022). "For example, imatinib is considered a definitive treatment for patients with HES in myeloid neoplasms (usually MDS/MPNs) and FIP1L1-PDGFRA rearrangement or PDGFRA/B-re-arranged neoplasms." (PMID 34935570, 2022). "RNA-seq may be a new diagnostic method when RARA rearrangements are failed to be identified by conventional methods, because of the obvious transcriptomic difference between APL with FIP1L1::RARA and myeloid neoplasms." (PMID 36776354, 2022).
lymphoid neoplasm (7 papers, 2014 to 2025). A neoplasm composed of a lymphocytic cell population which is usually malignant (clonal) by molecular genetic and/or immunophenotypic analysis. "Bone marrow studies confirmed an FIP1L1-platelet-derived growth factor receptor α-positive myeloid/lymphoid neoplasm." (PMID 41379052, 2025). "Prior to that, rearrangement in PGDFR-α was found in myeloid and lymphoid neoplasms with esinophilia where PDGFR-α is fused to Flip1-like 1 gene (FIP1L1) (FIP1L1-PDGFR-α)." (PMID 24744988, 2014). "In two other cases (20%), a FIP1L1-PDGFRA fusion was detected, which established the diagnosis of myeloid/lymphoid neoplasms with PDGFRA rearrangement according to the WHO 2016 classification." (PMID 35454892, 2022).
idiopathic hypereosinophilic syndrome (6 papers, 2008 to 2025). "In 2003, the FIP1L1–PDGFRA fusion was identified in patients with idiopathic hypereosinophilic syndrome and its presence redefined such patients having a neoplasm instead of idiopathic hypereosinophilic syndrome." (PMID 28791287, 2017). "The fusion protein FIP1L1-PDGFRa, a constitutively activated tyrosine kinase found in as many as half of those with the idiopathic hypereosinophilic syndrome, has emerged as a therapeutic target for imatinib." (PMID 19823676, 2009). "The fusion protein FIP1L1-PDGFRα, a constitutively activated tyrosine kinase found in as many as half of those with the idiopathic hypereosinophilic syndrome, has emerged as a therapeutic target for imatinib." (PMID 18301727, 2008). "Although the FIP1L1–PDGFRA fusion—well established in idiopathic hypereosinophilic syndrome—has not been identified in IFPs, it illustrates how PDGFRA dysregulation can drive marked eosinophilic proliferation." (PMID 41562800, 2025). "Normal cellularity with eosinophilic proliferation in the bone marrow and negative FIP1L1–PDGFRA raised the diagnosis of idiopathic hypereosinophilic syndrome." (PMID 36042524, 2022).
leukemia (6 papers, 2009 to 2022). A malignant (clonal) hematologic disorder, involving hematopoietic stem cells and characterized by the presence of primitive or atypical myeloid or lymphoid cells in the bone marrow and the blood. "As a novel regulator for APA events, FIP1L1 can regulate the 3’UTR lengthening of leukemia-associated genes, including NRAS, BAALC, and MAPKAPK3." (PMID 34195183, 2021). "FIP1L1 is also associated with a fusion gene contributing to the pathogenesis of leukemia and hypereosinohpilic syndrome." (PMID 30157244, 2018). "Reasons for different phenotypes of leukemia caused by FIP1L1::RARA remain unknown." (PMID 36776354, 2022). "Their fusion gene was respectively generated between exon 15 or 13 of FIP1L1 and exon 3 of RARA, while the reason for two different phenotypes of leukemia caused by FIP1L1–RARA is still unknown." (PMID 34249738, 2021). "Interestingly, both overexpression and knockdown of FIP1L1 are harmful to leukemia cells, demonstrating that mild alteration of gene expression may dramatically impact on cell fitness." (PMID 34195183, 2021). "Study indicates FIP1L1::RARA may interfere with FIP1L1 function, resulting in leukemia with monocytic features." (PMID 36776354, 2022).
glioma (5 papers, 2016 to 2023). A benign or malignant brain and spinal cord tumor that arises from glial cells (astrocytes, oligodendrocytes, ependymal cells). "In IDH mutated gliomas, this mechanism leads to the close interaction of FIP1L1 gene and Platelet-Derived Growth Factor Receptor, Alpha Polypeptide (PDGFRA) gene, which are normally confined to separate loop domains." (PMID 27723796, 2016). "Amplification of this region may lead to poorer outcomes as PDGFRA is a putative oncogene in glioma and FIP1L1 is constitutively expressed in oligodendrocyte precursor cells." (PMID 35852875, 2022). "This allows the constitutive enhancer FIP1L1 to interact aberrantly with PDGFRA, a prominent glioma oncogene." (PMID 27723796, 2016). "Thus, the MSI2/SNORD12B/FIP1L1/ZBTB4 positive feedback loop plays a crucial role in regulating the glycolipid metabolism of GBM cells and provides a potential drug target for glioma treatment." (PMID 34047477, 2021).
acute myeloid leukemia (4 papers, 2014 to 2025). Acute myeloid leukemia (AML) is a group of neoplasms arising from precursor cells committed to the myeloid cell-line differentiation. "The diagnosis of acute myeloid leukemia or myeloid sarcoma with a FIP1L1-PDGFRA rearrangement is extremely rare, with only a handful of case reports in the literature." (PMID 26457233, 2015). "Herein, we present a case report of a patient in whom the FIP1L1-PDGFRA was discovered as he evolved from CMML to acute myeloid leukemia (AML)." (PMID 24669761, 2014). "We herein present the case of a patient in whom FIP1L1-PDGFRA was discovered at the time of evolution from chronic myelomonocytic leukemia (CMML) to refractory acute myeloid leukemia and how therapy with imatinib resulted in durable complete remission." (PMID 24669761, 2014). "Fusion gene testing was completed in five patients, with cases 4 and 5 demonstrating FIP1L1::PDGFRA fusion gene positivity, and case 6 with TLS::ERG(+)acute myeloid leukemia." (PMID 41145290, 2025). "Notably, clonal acquisition of FIP1L1-PDGFRA has not been reported in the setting of acute myeloid leukemia evolving from CMML." (PMID 24669761, 2014).
systemic mastocytosis (4 papers, 2009 to 2022). Systemic mastocytosis (SM) comprises a heterogeneous group of rare acquired and chronic hematological malignancies that are related to an abnormal proliferation of mast cells in tissue, including bone marrow, with or without skin involvement. "Two male patients with splenomegaly carried the FIP1L1-PDGFRA rearrangement, whilst 2 others were ultimately classified as suffering from idiopathic hypereosinophlic syndrome (HES) and one from systemic mastocytosis." (PMID 19187542, 2009).
endocarditis (3 papers, 2023 to 2025). Inflammation of the endocardium. "Reported is a case of chronic eosinophilic leukaemia (CEL) with a FIP1L1-PDGFRA rearrangement, diagnosed in a 31-year-old patient presenting with Loeffler endocarditis." (PMID 40384954, 2025). "A case report described FIP1L1-PDGFR alpha fusion gene-positive myeloid leukemia in patients with eosinophilic syndrome affecting the heart and leading to Loeffler endocarditis." (PMID 39735860, 2024).
eosinophilic disorders (3 papers, 2020 to 2025). "This case highlights the complexities involved in treating FIP1L1-PDGFRA T674I-positive eosinophilic disorder, especially when compounded by additional mutations like PTPN11." (PMID 40141849, 2025). "This case illustrates the therapeutic challenges associated with FIP1L1-PDGFRA T674I-positive eosinophilic disorder, especially when compounded by the PTPN11 mutation." (PMID 40141849, 2025). "The convergence of Loeffler endocarditis with CEL, particularly in the context of FIP1L1-PDGFRA rearrangement, underscores the complexity of eosinophilic disorders with cardiovascular involvement." (PMID 40384954, 2025).
glioblastoma (3 papers, 2022 to 2025). The most malignant astrocytic tumor (WHO grade IV). "Four of these seven cases relate to glioblastoma in which fusion pairs CAPZA2-MET and FIP1L1-PDGFRA, CAPZA2-MET and MET-MET, EGFR VIII and PTPRZ1-MET, PTPRZ1-MET and TBL1XR1-PIK3CA were identified." (PMID 35984852, 2022). "This includes the two novel fusions genes we have identified in glioblastoma, TBL1XR1-PIK3CA and FIP1L1-PDGFRA." (PMID 35324914, 2022). "Interestingly, a broad range of actionable fusion genes were identified in this cohort of glioblastomas including EGFR-SEPT, EFGR intragenic recombination, FGFR3-TACC3, PTPRZ1-MET, CAPZA2-MET, METex14 skipping, AGK-BRAF, EGFR Viii, TBLXR1-PIK3CA and FIP1L1-PDGFRA." (PMID 35324914, 2022). "Moreover, two of these fusions, TBL1XR1-PIK3CA and FIP1L1-PDGFRA, have not been previously reported in glioblastoma to our knowledge." (PMID 35324914, 2022).
juvenile myelomonocytic leukemia (3 papers, 2021 to 2022). A myelodysplastic/myeloproliferative neoplasm of childhood that is characterized by proliferation principally of the granulocytic and monocytic lineages. "In 2007, the FIP1L1/RARA fusion gene was first reported as a novel RARA-associated fusion gene in a patient with juvenile myelomonocytic leukemia (JMML)." (PMID 34249738, 2021). "The FIP1L1::RARA fusion gene was first reported as a novel RARA-associated fusion gene in a 20-month-old child with juvenile myelomonocytic leukemia (JMML), no other mutations in N-Ras, K-Ras, or PTPN11 were detected." (PMID 36776354, 2022). "Interestingly, the same FIP1L1-RARA transcript, whose breakpoint was at exon-15 of FIP1L1 and the exon-3 of RARA, generated not only APL but also juvenile myelomonocytic leukemia, indicating the plasticity of FIP1L1-RARA-positive leukemic initial cells." (PMID 33957999, 2021).
myeloid sarcoma (3 papers, 2015 to 2022). A tumor mass composed of myeloblasts or immature myeloid cells. "The finding of a FIP1L1-PDGFRA rearrangement in a patient with refractory myeloid sarcoma was an unexpected finding only discovered because of clinical gene panel testing that is performed on all malignancies presenting to our institution." (PMID 26457233, 2015). "A 28-month-old girl with FIP1L1::RARA and complex karyotype was diagnosed with APL complicated by the de novo myeloid sarcoma." (PMID 36776354, 2022). "Moreover, the cells with a detected FIP1L1-PDGFRA rearrangement also contained trisomy 8, which was a previously demonstrated marker of this patient’s myeloid sarcoma." (PMID 26457233, 2015).
acute lymphoblastic leukemia (2 papers, 2021 to 2022). Leukemia with an acute onset, characterized by the presence of lymphoblasts in the bone marrow and the peripheral blood. "RNA sequencing (RNA-seq) of six patients (three cases of acute lymphoblastic leukemia (ALL), one case of myelodysplastic syndrome (MDS), one case of acute megakaryoblastic leukemia (M7), and one case of APL with FIP1L1::RARA) were performed." (PMID 36776354, 2022).
acute promyelocytic leukemia (2 papers, 2022). An aggressive form of acute myeloid leukemia (AML), characterized by arrest of leukocyte differentiation at the promyelocyte stage, due to a specific chromosomal translocation t(15;17) in myeloid cells. "The two adult patients with FIP1L1::RARA fusion were diagnosed as acute promyelocytic leukemia (APL)." (PMID 35819517, 2022). "FIP1L1::RARA fusion could also raise the possibility of acute promyelocytic leukemia, although typical features are lacking (no increase of promyelocytes with Auer rods, no disseminated intravascular coagulation)." (PMID 35819517, 2022).
bone marrow disease (2 papers, 2016 to 2025). "Subsequently, real-time quantitative PCR, or FISH and flow cytometry lymphocyte phenotyping, were performed in assessing FIP1L1-PDGFRA gene fusion, rare mutations and rearrangements, and clonal or aberrant T-cell populations in order to exclude clonal bone marrow disease." (PMID 40283978, 2025).
breast carcinoma (2 papers, 2020 to 2024). "The skipping FIP1L1 (exon 13) modulated by CDYL2a was found to promote cell proliferation in breast cancer." (PMID 38735973, 2024). "Collectively, these results suggest that CDYL2a promotes breast cancer cell proliferation through, at least partly, regulating the alternative splicing of FIP1L1, NKTR, and ADD3 genes." (PMID 32373210, 2020).
colon cancer (2 papers, 2019 to 2020). "In support of our findings, an exon skipping event of FIP1L1 has been documented in colon cancer." (PMID 32373210, 2020).
myeloid leukemia (2 papers, 2023 to 2024). A clonal proliferation of myeloid cells and their precursors in the bone marrow, peripheral blood, and spleen. "After hematological evaluation, genetic tests, and ruling out reactive causes of HE, a diagnosis of positive FIP1L1-PDGFRα myeloid leukemia was established." (PMID 37238279, 2023).
Splenomegaly (2 papers, 2009 to 2014). Abnormal increased size of the spleen. "In our study, both patients with FIP1L1-PDGFRA rearrangement were male and exhibited splenomegaly, similar to the majority of the positive patients reported in the literature." (PMID 19187542, 2009).